Y_RNA (Y RNA )
Gene: Miscellaneous RNA gene on chromosome 3 (101,647,421 to 101,647,522, forward strand). Ensembl gene ENSG00000201511.
Homologues: Orthologues: chimpanzee Y_RNA (100% identical), macaque Y_RNA (97% identical), guinea pig Y_RNA (88% identical). Paralogues in human: Y_RNA (88% identical), RNY3 (87% identical), Y_RNA (87% identical), Y_RNA (86% identical), RNY3P1 (85% identical), Y_RNA (85% identical), Y_RNA (84% identical), RNY3P14 (83% identical), RNY3P16 (83% identical), RNY3P3 (83% identical), RNY3P5 (83% identical), Y_RNA (83% identical), and 94 more.